APAF1 (apoptotic peptidase activating factor 1)
Diseases named in the same sentence as APAF1 in open-access papers (continued):
Sharing a sentence is not in itself a finding about the gene and the disease.
tumor (continued). "However, the expression of Apaf-1, PUMA and XAF1 expression did not correlate with tumor thickness." (PMID 16755297, 2006).
infection (32 papers, 2002 to 2026). The state of being infected such as from the introduction of a foreign agent such as serum, vaccine, antigenic substance or organism. "Given the centrality of Apaf-1 in the initiation of intrinsic apoptosis, our results propose a new mechanism by which cell fate decisions during stress or infection can be made at the upstream innate sensing stage." (PMID 39833169, 2025). "Nonetheless, hnRNP A1 cleavage and further increases in apaf-1 levels occur at late times post-infection." (PMID 31498791, 2019). "Apaf-1 levels remained relatively constant between 5–10 hours post-infection, and then increased ~70–80% above time-zero at late times post-infection, between 12 and 24 hours." (PMID 31498791, 2019). "Later in infection, 3Cpro cleaves hnRNP A1 resulting in apaf-1 translation and subsequent apoptosis for virus spreading." (PMID 31498791, 2019). "The cleavage profile of eIF4G is consistent with increasing apaf-1 protein levels beginning at 3 hours post-infection being due to apaf-1 IRES-dependent translation." (PMID 31498791, 2019). "In ECs, infection with P. gingivalis displayed anti-apoptotic effects through a decrease of Bax-1 and Apaf-1 and an increase of anti-apoptotic Bcl-2 expression in EC." (PMID 30297793, 2018). "Infection with Pg increased significantly caspase-3, -9, Bax-1 and Apaf-1 expression and decreased Bcl-2 expression in comparison with Ox-LDL pre-treated cells." (PMID 27124409, 2016). "Essentially, API5 downregulates APAF1 and prevents activation of caspases, thus impeding apoptosome formation under infection conditions." (PMID 26673663, 2015). "Several reports have shown that an increased neuronal expression of Bcl-2, Beclin, Bax and decreased expression of Apaf-1 on fibroblast turned cells more resistant to apoptotic cell death induced by SinV infection." (PMID 22485151, 2012). "However, p65 and p38 phosphorylation still increased at 12 h post-infection in Sting−/− cells and the knockout of Apaf-1 inhibited HSV-1-induced p-p65 and p-p38." (PMID 39833169, 2025). "Most of the Apaf-1+/− mice died on Day 5 after infection, while 80% of WT mice survived." (PMID 39833169, 2025). "However, between 3–5 hours post-infection, apaf-1 levels increased and returned to near normal (i.e., the time-zero level)." (PMID 31498791, 2019). "However, there may be additional mechanisms, albeit unknown ones, at early times post-infection that regulate cap-independent synthesis of apaf-1." (PMID 31498791, 2019). "To determine the specific mechanism, we examined the levels of apoptosis-related genes (BAX, APAF-1, TNF-α, Caspase-9, Caspase-3, and BCL-2) in EBL cells following infection with M. bovis." (PMID 39308873, 2024). "We found that the expression of several molecules was upregulated following infection with C. parvum in HCT-8 cells, including FasL, TRAIL, Apaf-1, and Caspase-8." (PMID 35974384, 2022). "Bak and Apaf-1 in the DHAV-1 infection group increased significantly at 60 h and 72 h after infection, whereas Cyt c was downregulated at 120 h after infection." (PMID 31727985, 2019).
infection (continued). "Results demonstrated that the expression levels of Apaf-1, Bax, Bim, and PUMA were increased after infection with OV.HDAC1, OV.p73, as well as OV.shHDAC1.p73 compared to the parental OV.Luc." (PMID 25071017, 2014). "Through TUNEL assay, flow cytometry, and apoptotic pathway analysis, Our analysis revealed that H5N6 AIV infection markedly upregulates apoptotic genes such as Fas, FADD, caspase-8, BAK, cytochrome c, APAF1, caspase-9, and caspase-3 (P < 0.05), thereby promoting apoptosis in DEFs." (PMID 41992349, 2026). "Significant amounts of HSV-1 were detected in the brains of Apaf-1+/− mice but not in WT mice 3 days after infection." (PMID 39833169, 2025). "Plant proteins from this group with the central Apaf1/R/CED4-like NBD (TIR-NBARC-LRR, or TNLs) act as immune receptors that bind pathogen effectors directly or detect their manipulation of host physiology during infection." (PMID 35143666, 2022). "The results showed that the incremental increase in infection rate was absent, but there was no further decline in the rate at the higher doses of the vector containing the apaf-1 gene." (PMID 26290316, 2015). "To distinguish between necrosis by viral replication and apoptosis by repression of HDAC1 and overexpression of p73, we monitored the changes in expression of the pro-apoptotic genes Apaf-1, Bax, Bim, and PUMA 48 hours after infection of SK-Mel-147 cells with the oncolytic viruses by real-time PCR." (PMID 25071017, 2014). "Interestingly, Chlamydia required caspase-9 activation for its infection, but this did not lead to caspase-3 activation or apoptotic events, and caspase-9 activation occured without Apaf-1." (PMID 26290316, 2015).
neurodegenerative disease (4 papers, 2015 to 2025). A disorder of the central nervous system characterized by gradual and progressive loss of neural tissue and neurologic function. "APAF1 (apoptotic peptidase activating factor) was reported as a potential drug target for neurodegenerative diseases and APAF1 dominant negative inhibitor can prevent MPTP toxicity as antiapoptotic gene therapy for Parkinson’s disease." (PMID 40585238, 2025).
APAF1 also shares sentences with these, for which no sentence is quoted: acute myeloid leukemia (5 papers); neuroblastoma (4); amyotrophic lateral sclerosis (2); chronic lymphocytic leukemia (2); Hypertension (2); osteosarcoma (2); acute kidney injury (1); adenomyosis (1); ankylosing spondylitis (1); Autoimmunity (1); bacterial infection (1); benign tumors (1); brain cancer (1); brain tumours (1); cardiomyopathy (1); cerebral infarction (1); cervix adenocarcinoma (1); chronic pancreatitis (1); clear-cell renal cell carcinoma (1); clubfoot (1); coronary artery disease (1); cutaneous squamous cell carcinoma (1); epilepsy (1); head and neck squamous cell carcinoma (1); heart disease (1); heart failure (1); hepatitis B (1); hepatitis C (1); Hydrocephalus (1); immunodeficiencies (1).
A further 24 diseases each share a sentence with APAF1 in 1 paper.